CXorf51A (chromosome X open reading frame 51A)
Synonyms: CXorf51; CXorf51B
Gene: Protein-coding gene on chromosome X (146,814,106 to 146,814,744, reverse strand). Ensembl gene ENSG00000224440.
Homologues: Orthologues: chimpanzee CXHXorf51B (99% identical). Paralogues in human: CXorf51B (100% identical).